RPE65 (retinoid isomerohydrolase RPE65)
Diseases named in the same sentence as RPE65 in open-access papers (continued):
Sharing a sentence is not in itself a finding about the gene and the disease.
Leber congenital amaurosis (continued). "The form of Leber congenital amaurosis (LCA) that has now been treated is caused by that is caused by an abnormality in the visual (retinoid) cycle resulting from deficiency of RPE65." (PMID 26246977, 2015). "In clinical trials, three independent groups reported vision improvements upon the viral-mediated delivery of the Rpe65 gene in patients with Rpe65-associated Leber’s congenital amaurosis (LCA)." (PMID 26062170, 2015). "RPE65-associated Leber congenital amaurosis (LCA), a type of early-onset RP, has been shown to be highly amenable to treatment with sub-retinal gene therapy in mice, dogs and humans (6, 7, S11)." (PMID 24665880, 2014). "Mutations in RPE65 gene were primarily reported in patients with Leber congenital amaurosis (LCA, MIM204000)." (PMID 25383945, 2014). "Mutations in the RPE65 gene cause not only subtype II of Leber congenital amaurosis (LCA) but also early-onset severe retinal dystrophy (EOSRD)." (PMID 25383945, 2014). "Several clinical trials have recently shown that the subretinal injection of RPE65-encoding AAV yields significant visual improvement in patients with Leber’s congenital amaurosis (LCA), a severe form of retinal degeneration affecting children." (PMID 23613884, 2013). "Recent developments in retinal gene therapy have led to the successful treatment of patients with Leber’s congenital amaurosis (LCA) due to mutations in RPE65." (PMID 23593201, 2013). "RPE65 acts as the key retinoid isomerohydrolase in the visual cycle; mutations in this enzyme lead to retinal disease (Leber congenital amaurosis 2 (LCA2) and retinitis pigmentosa) resulting in blindness." (PMID 23209628, 2012). "Several methods have already been created for large-scale production of recombinant AAV (rAAV), and it is already in clinical trials for Leber congenital amaurosis (LCA) associated with mutations in RPE65." (PMID 23077406, 2012). "Patients with Leber congenital amaurosis caused by RPE65 mutations have been treated successfully by gene replacement therapy." (PMID 21677792, 2011). "The success of the RPE65−/− dog gene therapy experiments was crucial in the development of human clinical trials to treat patients affected with Leber congenital amaurosis (LCA) or early onset retinal degeneration linked to a mutation in RPE65." (PMID 19223988, 2009). "Similarly, multifunctional lipid nanoparticles modified with all‐trans‐retinamine have been shown to deliver plasmid DNA to the retina in the Rpe65−/− mouse model for the treatment of Leber's congenital amaurosis caused by RPE65 gene mutations." (PMID 40859956, 2025). "A landmark product is voretigene neparvovec-rzyl (Luxturna, Spark Therapeutics, Inc.), the first FDA-approved gene therapy for a retinal condition, which treats patients with biallelic RPE65 mutations causing Leber congenital amaurosis (LCA) or early-onset retinitis pigmentosa (RP)." (PMID 41155120, 2025). "Notably, AAV-based therapies, such as Luxturna (using AAV2 for RPE65 mutations causing Leber congenital amaurosis) and Zolgensma (using AAV9 for spinal muscular atrophy by replacing the SMN1 gene), have shown remarkable therapeutic outcomes." (PMID 41235102, 2025). "Finally, we demonstrate an RPE65 mutation correction in a Leber congenital amaurosis 2 (LCA2) patient-specific iPSC line using enFnCas9 adenine base editor, highlighting its therapeutic utility." (PMID 38942756, 2024). "Indeed, patients exhibiting mutations affecting LRAT and RPE65 are responsible for dramatic progressive ocular diseases called Leber congenital amaurosis and Retinitis pigmentosa, and these pathologies are characterized by several retinal dystrophies." (PMID 37798757, 2023). "For example, mutations on the RPE65 gene cause Leber Congenital Amaurosis (LCA) but also some forms of Retinitis Pigmentosa (RP), Bardet Biedl Syndrome (BBS), Congenital Stationary Night Blindness (CSNB) and Usher syndrome (USH), with a very wide spectrum of clinical manifestations." (PMID 37762059, 2023).
Leber congenital amaurosis (continued). "While these disorders have long been considered untreatable, recent advances in molecular biology have led to the first FDA-approved gene therapy for a retinal dystrophy, voretigene neparvovec-rzyl (LUXTURNA) for RPE65-associated Leber congenital amaurosis (LCA)." (PMID 34768969, 2021). "Advancements in molecular biology and a detailed understanding of the pathophysiology of retinal disease allowed for the development of the first FDA-approved gene therapy for biallelic RPE65-associated Leber congenital amaurosis (LCA), voretigene neparvovec-rzyl (LUXTURNA)." (PMID 34768969, 2021). "Among these clinical trials, voretigene neparvovec-rzyl (Luxturna), an adeno-associated virus vector-based gene therapy drug, was approved by the FDA for treating patients with confirmed biallelic RPE65 mutation-associated Leber Congenital Amaurosis (LCA) in 2017." (PMID 33926102, 2021). "Following the approval of an IRD gene replacement therapy for Leber’s congenital amaurosis due to RPE65 mutations, there has been an intensive international research effort to identify the optimal gene therapy approaches for a range of IRDs and many are now undergoing clinical trials." (PMID 35069693, 2021). "Current AAV retinal gene therapy trials and therapeutic protocols, in the case of voretigene neparvovec for RPE65-associated Leber congenital amaurosis, generally include a perioperative period of systemic immunosuppression with prednisolone to reduce the risk of retinal inflammation." (PMID 32674481, 2020). "Leber congenital amaurosis is a group of inherited retinal dystrophies that cause severe sight impairment in childhood; RPE65-deficiency causes impaired rod photoreceptor function from birth and progressive impairment of cone photoreceptor function associated with retinal degeneration." (PMID 27653967, 2016). "Studies of animal models have already facilitated the development of powerful diagnostic tests and effective therapeutic strategies, such as gene therapy for Leber Congenital Amaurosis caused by defects in the retinal pigment epithelium-specific protein 65kDa (RPE65) gene." (PMID 22509100, 2012). "However, with the successful development of gene therapy for retinal dystrophies, such as for Leber congenital amaurosis due to RPE65 mutations, molecular diagnosis is of increasing importance to enroll patients in future clinical trials." (PMID 22128245, 2011). "Currently, the Luxturna RPE65 gene augmentation therapy is being used to treat patients with Leber congenital amaurosis (LCA) and retinitis pigmentosa (RP) carrying RPE65 variants." (PMID 41009968, 2025). "In December 2017, the FDA approved voretigene neparvovec‐rzyl (Luxturna), a gene therapy‐based drug, for the treatment of Leber congenital amaurosis (LCA) caused by biallelic retinal pigment epithelium‐specific 65‐kDa protein gene (RPE65)." (PMID 41392397, 2025). "Mutations in the RPE65 gene lead to a form of Leber congenital amaurosis (LCA), an inherited retinal degeneration." (PMID 40715346, 2025). "To date, only an inherited retinal disease, namely Leber’s congenital amaurosis, can be treated effectively by gene augmentation with voretigene neparvovec (Luxturna®, Spark Therapeutics, Pennsylvania, USA) via adenovirus-associated virus vectors transporting the RPE65 transgene into target cells." (PMID 40029473, 2025). "Leber congenital amaurosis (LCA) is the most common inherited cause of blindness in children, and homozygous loss-of-function mutations in RPE65 are one genetic cause of this disease." (PMID 41300177, 2025). "The purpose of this study was to describe a Japanese male patient with a novel variant in RPE65 associated with Leber congenital amaurosis (LCA)." (PMID 39359914, 2024). "Mutations in the retinoid isomerohydrolase gene (RPE65) are responsible for Leber congenital amaurosis (LCA) with an autosomal recessive inheritance and non-syndromic RP." (PMID 39280562, 2024).
Leber congenital amaurosis (continued). "Luxturna is a novel gene therapy medication used to treat a specific form of inherited retinal disease called Leber congenital amaurosis (LCA) or retinitis pigmentosa (RP) caused by mutations in the RPE65 gene." (PMID 38424595, 2024). "Biallelic pathogenic variants in the RPE65 gene cause Leber congenital amaurosis (LCA) (OMIM 204100) and severe early-onset retinitis pigmentosa (RP20; OMIM 613794)." (PMID 38002999, 2023). "Clinically, a majority of RPE65 variants (approximately 67%) are commonly associated with Leber congenital amaurosis (LCA) or retinitis pigmentosa (RP) phenotypes (approximately 16%), which have similar fundus manifestations." (PMID 37547722, 2023). "Leber congenital amaurosis (LCA), or early-onset retinal dystrophy, is caused by a mutation in the RPE65 gene that disrupts the retinoid cycle and ultimately leads to severe visual impairment." (PMID 37090805, 2023). "Luxturna is destined for the treatment of retinitis pigmentosa (RP) or Leber congenital amaurosis (LCA) associated with Rpe65 mutations." (PMID 35506982, 2022). "It is a rAAV2-based platform that delivers an RPE65 expression cassette to treat type 2 Leber Congenital Amaurosis (LCA), a recessive monogenetic retinal dystrophy caused by biallelic pathogenic mutation in the RPE65 gene." (PMID 36145679, 2022). "This modality of treatment has shown efficacy in clinical trials treating RPE65-associated Leber congenital amaurosis (LCA), CHM-associated choroideremia, CNGA3-related achromatopsia, and MERTK-associated retinitis pigmentosa." (PMID 36012955, 2022). "Biallelic pathogenic variants in RPE65 cause early-onset severe retinal dystrophy (EOSRD) or Leber congenital amaurosis (LCA)." (PMID 34938339, 2021). "Recently, gene therapy using an adeno-associated virus (AAV) vector has been shown to be effective in the treatment of a different IRD called Leber congenital amaurosis (LCA) caused by RPE65 variants." (PMID 34440414, 2021). "In 2008, various research groups reported the first studies testing the safety and efficacy of RPE65 gene therapy for patients with Leber congenital amaurosis (LCA) caused by a defect in this gene." (PMID 34001227, 2021). "The introduction of gene therapy, such as Voretigene Neparvovec-rzyl-LuxturnaTM for the treatment of biallelic Retinal Pigment Epithelium 65 (RPE65) associated Leber Congenital Amaurosis (LCA), has been a significant development." (PMID 34412697, 2021). "Luxturna aims to reverse blindness in patients with Leber congenital amaurosis (LCA) caused by biallelic RPE65 mutations." (PMID 32477041, 2020). "Mutations of the gene encoding RPE65 cause Leber congenital amaurosis (LCA) retinitis pigmentosa (RP)." (PMID 30695025, 2019). "Loss of RPE65 function results in death of photoreceptors and causes Leber congenital amaurosis (LCA), a severe form of RP25." (PMID 29666392, 2018). "As leading example, treatment of RPE65-dependent Leber congenital amaurosis (LCA) by subretinal injection of adeno-associated viral vectors (AAV) has shown promising results in Phase 3 clinical trials and is expected to reach the clinic soon." (PMID 28925755, 2017). "An autosomal recessive IRD called Leber congenital amaurosis (LCA), caused by mutations in the key retinoid cycle gene encoding RPE65, has recently been in clinical trials." (PMID 26246977, 2015). "More than 60 different mutations in the RPE65 gene have been associated with inherited retinal dystrophies including Leber congenital amaurosis (LCA) and autosomal recessive RP." (PMID 23878505, 2013). "Mutations in RPE65 cause the childhood blindness disorder known as Leber congenital amaurosis (LCA), as well as autosomal recessive retinitis pigmentosa (RP)." (PMID 22509104, 2012). "The RPE65 gene has been associated with autosomal recessive retinitis pigmentosa as well as autosomal recessive Leber congenital amaurosis (LCA)." (PMID 22131872, 2011).
Leber congenital amaurosis (continued). "RPE65 is an essential molecule in the retinoid-visual cycle, and RPE65 gene mutations cause the congenital human blindness known as Leber congenital amaurosis (LCA)." (PMID 17594175, 2007). "Inherited Retinal Diseases, such as Leber Congenital Amaurosis (LCA), is caused by mutations in the RPE65 gene, leading to progressive vision loss." (PMID 41235102, 2025). "Gene therapy has now entered clinical practice, with voretigene neparvovec (Luxturna®) for RPE65-mediated Leber congenital amaurosis representing a landmark clinical milestone." (PMID 41463332, 2025). "The Multi Luminance Mobility Test (MLMT) was used as a primary outcome measure in the landmark clinical trial of voretigene neparvovec (Luxturna) for RPE65-related Leber’s congenital amaurosis, the first approved gene therapy in ophthalmology." (PMID 40436455, 2025). "For example, AAV2 effectively transduces photoreceptors and retinal pigment epithelium (RPE), which forms the basis for Voretigene neparvovec-rzyl (LuxturnaTM), a treatment for RPE65-mediated Leber congenital amaurosis that shows sustained visual improvement." (PMID 40725503, 2025). "There are animal models, including mouse-based ones, that faithfully resemble human retinal degenerations to the extent that this has contributed to now-established therapies, like that for the rpe65 gene in Leber’s congenital amaurosis." (PMID 38542418, 2024). "For example, gene replacement therapy for RPE65-related Leber congenital amaurosis aims to restore protein function." (PMID 39439625, 2024). "Genetic and vision restoration treatments are under development and one gene therapy treatment, Luxturna, is currently approved for one specific type of inherited eye disease, the RPE65-related Leber congenital amaurosis." (PMID 39232248, 2024). "Biallelic mutations in RPE65, which encodes the isomerase of the retinoid cycle, have been associated with retinitis pigmentosa type 20 (RP) and Leber congenital amaurosis type 2 (LCA)." (PMID 37892166, 2023). "The same RPE65 gene is also involved in the development of the following retinal dystrophies: Leber Congenital Amaurosis (LCA), Retinitis Pigmentosa (RP), Bardet Biedel (BBS), Congenital Stationary Night Blindness (CSNB) and Usher Syndrome (USH)." (PMID 37762059, 2023). "For instance, the treatment of Leber congenital amaurosis with the RPE-specific 65KDa gene (RPE65) carried by the AAV vector has demonstrated significant improvements in visual function." (PMID 38145048, 2023). "Three successful clinical trials were completed regarding the safety of subretinal injection of 65 kDa retinal pigment epithelium-specific protein (RPE65) expressed by an AAV vector for Leber congenital amaurosis." (PMID 36769387, 2023). "RPE65-linked IRD typically manifests as Leber congenital amaurosis (LCA) or early-onset severe retinal dystrophy (EO[S]RD), characterized by severe visual impairment from birth or early infancy with light staring and profound nyctalopia accompanied by nystagmus and poor pupillary light responses." (PMID 36672611, 2022). "Patients with pathogenic variants in the RPE65 gene have been presented with autosomal recessive RP, fundus albipunctatus, cone-rod dystrophy, and, most frequently, Leber congenital amaurosis (LCA) and early-onset severe retinal dystrophy (EOSRD) (LCA2, OMIM # 204100)." (PMID 35162940, 2022). "Of the available constructs, AAV2 has the most extensive track record and safety profile for intraocular gene therapy including in clinical trials, where they have been used to deliver RPE65 in Leber congenital amaurosis." (PMID 35639753, 2022). "For example, leber congenital amaurosis (LCA) is an inherited retinal degenerative disease caused by mutations in different genes, including CEP290, GUCY2D, CRB1, and RPE65." (PMID 36556333, 2022). "Luxturna, a gene therapy for the previously incurable RPE65-Leber congenital amaurosis (LCA), which involves blindness, improves the ability to detect light." (PMID 35742919, 2022).
Leber congenital amaurosis (continued). "With the same idea to validate the safety of LV use for gene therapy clinical trials, but this time to treat RPE65-related Leber congenital amaurosis, we subretinally injected LV-RPE65 (2 doses tested: 2.8 × 105 IU and 2.8 × 106 IU in 100 μL) in healthy NHPs." (PMID 36015231, 2022). "Luxturna® uses adeno-associated virus serotype 2 (AAV2) as a delivery vehicle to carry the wild-type Retinal Pigment Epithelium 65 (RPE65) gene into the retinal cells with RPE65 mutation for treating patients with Leber congenital amaurosis (LCA), a rare form of inherited vision loss." (PMID 36463195, 2022). "Likewise, the most prevalent Leber congenital amaurosis (LCA) causative RPE65 mutation, R91W, destabilizes RPE65 proteins." (PMID 36138817, 2022). "Currently, more than 138 pathogenic variants in the RPE65 gene have been associated with different subtypes of IRDs such as retinitis pigmentosa, severe early childhood onset retinal dystrophy and Leber congenital amaurosis (LCA)." (PMID 36429068, 2022). "Luxturna is an AAV2-based vector that delivers the retinoid isomerohydrolase RPE65,213 the effected gene in Leber’s congenital amaurosis, which causes progressive blindness." (PMID 33558455, 2021). "ROs have also been used to identify the disease mechanisms of Leber’s congenital amaurosis (LCA)-related RPE65, CEP290, AIPL1 and CRX." (PMID 34719743, 2021). "While there are several mutations of visual cycle proteins associated with Leber’s congenital amaurosis (LCA), LCA caused by mutations of RPE65 is observed in nearly 6% of cases." (PMID 34476420, 2020). "To date, almost 200 loss-of-function mutations have been identified within the RPE65 gene causing inherited retinal dystrophies, most notably Leber congenital amaurosis (LCA) and autosomal recessive retinitis pigmentosa (arRP), which are both severe and early onset disease entities." (PMID 33261050, 2020). "Leber congenital amaurosis and macular degeneration were enriched in C0, which specifically expressed RPE65, OTX2, LRAT, and BEST1." (PMID 33072724, 2020). "In Leber congenital amaurosis (LCA), mutations in either lecithin-retinol acyltransferase (LRAT) or retinoid isomerase (RPE65) lead to S-opsin aggregation and subsequent ER stress, which in turn results in rapid degeneration of cone cells." (PMID 31757001, 2019). "Several gene therapy trials in the retina are currently underway and gene therapy has been shown to be effective for some diseases such as RPE65-Leber congenital amaurosis." (PMID 30498755, 2018). "Multiple groups subsequently launched clinical trials to deliver subretinal RPE65 via an AAV vector to patients with Leber congenital amaurosis, reinvigorating research in gene therapy." (PMID 28134823, 2017). "Recently, one form of early-onset autosomal recessive IRD, Leber congenital amaurosis (LCA) caused by mutations in RPE65 (retinal pigment epithelium-specific protein 65 kDa) gene, has responded with some improvement of vision to gene augmentation therapy and oral retinoid administration." (PMID 26246977, 2015). "Mutations in RPE65 and LRAT cause both RP and Leber congenital amaurosis (LCA) in humans (for a review see Ref 1)." (PMID 26656277, 2015). "In the present study, we generated a vector using components very similar to those of the vector that we used successfully in Phase I/II studies in a clinical trial for Leber Congenital Amaurosis due to RPE65 mutations (LCA-RPE65), an AAV vector with serotype 2 capsid." (PMID 23667438, 2013). "In the Rpe65−/− mouse model of Leber's congenital amaurosis, we previously observed decreased expression of αA- and αB-crystallins during disease progression, which was correlated with Bax pro-death activity and photoreceptor apoptosis." (PMID 23383327, 2013). "Confirming the dynamism in this field, RPE65 gene replacement for Leber congenital amaurosis (LCA) is now in Phase I/II clinical trials driven by three different teams all using AAV2/2 vectors." (PMID 21304899, 2011).